STAT5A (signal transducer and activator of transcription 5A)
Description:
Carries out a dual function: signal transduction and activation of transcription. Mediates cellular responses to the cytokine KITLG/SCF and other growth factors. Mediates cellular responses to ERBB4. May mediate cellular responses to activated FGFR1, FGFR2, FGFR3 and FGFR4. Binds to the GAS element and activates PRL-induced transcription. Regulates the expression of milk proteins during lactation.
Synonyms: STAT5; MGF
Tractability: Small molecule: a structure with a bound ligand is known; a high-quality ligand is known; it belongs to a druggable protein family. PROTAC: UniProt records ubiquitination sites on it; ubiquitination databases record sites on it; its protein half-life has been measured; a small molecule that binds it is known.
Target class: Transcription factor
Gene: Protein-coding gene on chromosome 17 (42,287,547 to 42,311,943, forward strand). Ensembl gene ENSG00000126561.
Subcellular location: Cytoplasm; Nucleus
Subcellular location (Human Protein Atlas): Cytosol; Nucleoplasm
Pathways (Reactome):
Immune System: Growth hormone receptor signaling; Inactivation of CSF3 (G-CSF) signaling; Interleukin-15 signaling; Interleukin-2 signaling; Interleukin-20 family signaling; Interleukin-21 signaling; Interleukin-3, Interleukin-5 and GM-CSF signaling; Interleukin-7 signaling; Interleukin-9 signaling; Prolactin receptor signaling; STAT5 Activation; Signaling by CSF3 (G-CSF)
Disease: Nuclear events stimulated by ALK signaling in cancer; STAT5 activation downstream of FLT3 ITD mutants; Signaling by FLT3 fusion proteins; Signaling by cytosolic FGFR1 fusion mutants; Signaling by phosphorylated juxtamembrane, extracellular and kinase domain KIT mutants
Signal Transduction: Downstream signal transduction; Erythropoietin activates STAT5; Nuclear signaling by ERBB4; Signaling by Leptin; Signaling by SCF-KIT
Developmental Biology: Differentiation of naive CD4+ T cells to T helper 2 cells (Th2 cells)
Gene Ontology:
Molecular function: DNA-binding transcription factor activity; DNA-binding transcription factor binding; protein binding; DNA-binding transcription factor activity, RNA polymerase II-specific; RNA polymerase II cis-regulatory region sequence-specific DNA binding; DNA binding; DNA-binding transcription activator activity, RNA polymerase II-specific; phosphate ion binding; promoter-specific chromatin binding; sequence-specific DNA binding
Biological process: eosinophil differentiation; interleukin-15-mediated signaling pathway; interleukin-2-mediated signaling pathway; interleukin-3-mediated signaling pathway; interleukin-4-mediated signaling pathway; interleukin-5-mediated signaling pathway; interleukin-7-mediated signaling pathway; interleukin-9-mediated signaling pathway; negative regulation of T-helper 17 cell lineage commitment; positive regulation of blood vessel endothelial cell migration; positive regulation of endothelial cell proliferation; reelin-mediated signaling pathway; thrombopoietin-mediated signaling pathway; cell surface receptor signaling pathway via JAK-STAT; cytokine-mediated signaling pathway; defense response; growth hormone receptor signaling pathway via JAK-STAT; positive regulation of transcription by RNA polymerase II; regulation of cell population proliferation; regulation of multicellular organism growth; regulation of transcription by RNA polymerase II; response to peptide hormone; taurine metabolic process; regulation of DNA-templated transcription; regulation of hemopoiesis; and 1 more
Cellular component: cytoplasm; cytosol; nucleoplasm; nucleus; chromatin; RNA polymerase II transcription regulator complex
Genetic constraint (gnomAD): Loss-of-function variants: 26 observed, 99.05 expected, observed/expected ratio (o/e) 0.26, 90% interval 0.19 to 0.36. The synonymous counts are far from expectation, so gnomAD's model fits this gene poorly and the ratio says little. Missense variants: 629 observed, 1,012.7 expected, observed/expected ratio (o/e) 0.62, 90% interval 0.58 to 0.66. Synonymous variants: 322 observed, 409.22 expected, observed/expected ratio (o/e) 0.79, 90% interval 0.72 to 0.86.
Homologues: Orthologues: macaque STAT5A (99% identical), dog STAT5A (97% identical), pig STAT5A (97% identical), rat Stat5a (96% identical), mouse Stat5a (96% identical), rabbit STAT5A (96% identical), chimpanzee STAT5A (94% identical), guinea pig STAT5A (91% identical), tropical clawed frog stat5b (85% identical), zebrafish stat5a (77% identical), zebrafish stat5b (73% identical), Drosophila melanogaster Stat92E (32% identical). Paralogues in human: STAT5B (92% identical), STAT6 (36% identical), STAT3 (28% identical), STAT4 (27% identical), STAT1 (27% identical), STAT2 (25% identical).
Diseases named in the same sentence as STAT5A in open-access papers:
STAT5A is named in the same sentence as 181 diseases in open-access papers, as found by Europe PMC text mining. Sharing a sentence is not in itself a finding about the gene and the disease. The quoted sentences say what the papers report.
breast cancer (96 papers, 2004 to 2025). A primary or metastatic malignant neoplasm involving the breast. "In comparison, STAT5A shows favorable prognostic associations in breast cancer but detrimental effects in hematologic malignancies, whereas STAT5B appears predominantly tumor-suppressive across epithelial cancers and protective in B-cell lymphomas." (PMID 41301421, 2025). "STAT5A has been found to be negatively correlated with interferon-stimulated exonuclease gene 20 (ISG20) expression in breast cancer, where ISG20 is upregulated in metastases and is associated with aggressive and invasive tumor behavior." (PMID 40507264, 2025). "On one hand, there are studies that associate the STAT5A with survival of breast cancer tissues due to the role of STAT5A in promoting breast tissue proliferation." (PMID 38895458, 2024). "On the other hand, other studies associate expression of STAT5A gene with a better breast cancer prognosis, as the gene promotes mammary gland epithelial cell differentiation." (PMID 38895458, 2024). "Conversely, silencing of Notch3 expression by siNotch3 decreased STAT5A expression, supporting that STAT5A expression is positively associated with Notch3 in human breast cancer cell lines and breast cancer tissues." (PMID 38124049, 2023). "After adjusting for clinicopathological factors, high STAT5a expression remained significantly associated with favorable survival in breast cancer (lnHR = −0.6091 [−1.0810, −0.1372], P-value = 0.0114)." (PMID 37369132, 2023). "With potential tumor-suppressing function in breast cancer, the underlying molecular mechanism of STAT5A needs to be investigated." (PMID 38124049, 2023). "The present study demonstrates that Notch3 inhibits metastasis in breast cancer through inducing transcriptionally STAT5A, which was associated with tumor-infiltrating immune cells, providing a novel strategy to treat breast cancer." (PMID 38124049, 2023). "This showed that STAT3 is the most central protein governing communication with tumor-linked proteins in the breast cancer network, whereas STAT5a is the only STAT showing a direct interaction with ER." (PMID 37834225, 2023). "As expected, expression of the Notch3-target gene, STAT5A, was also found to be positively associated with the period of recurrence in patients with breast cancer (p < 1E-16, HR = 0.65)." (PMID 38124049, 2023). "In breast cancer cells, repression of hsa-miR-221 and hsa-miR-222 were associated to overexpression of STAT5A conferring a more aggressive tumor phenotype." (PMID 36176980, 2022). "Here, phosphorylation of S726-, S780-, and Y694-STAT5a in response to prolactin in MCF7 luminal breast cancer cells was investigated with STAT5a knockdown and rescue with Y694F-, S726A-, or S780A-STAT5a, where the phospho-sites were mutated." (PMID 34188118, 2021). "Loss of NMI in vivo caused a decrease in STAT5A activity in normal mammary epithelial as well as breast cancer cells." (PMID 34078871, 2021). "This indicates that not only phosphorylation of Y694, but also phosphorylation of S780 on STAT5a is involved in the clonogenicity of breast cancer, in that fewer MCF7 colonies were established with loss of the phospho-sites." (PMID 34188118, 2021). "For the first time, we have analyzed the loss of STAT5a serine phosphorylation on breast cancer phenotypic characteristics that fall within the hallmarks of cancer." (PMID 34188118, 2021). "Hemizygous loss of STAT5a in a tumor-prone WAP-Simian Virus 40 T antigen (TAg) transgenic mouse model significantly delayed mammary cancer progression, as evidenced by a reduction in tumor size and number." (PMID 32633727, 2020). "Low levels of STAT5A are associated with breast cancer progression and poor prognosis of patients with breast cancer." (PMID 27780928, 2016). "Here we quantify for the first time levels of Stat5a and Stat5b over breast cancer progression, and explore their potential association with clinical outcome." (PMID 23036105, 2012).
breast cancer (continued). "In breast cancer, loss of nuclear localized and tyrosine phosphorylated Stat5a/b is associated with poor prognosis and increased risk of antiestrogen therapy failure." (PMID 23036105, 2012). "Because STAT5a has been implicated in breast cancer migration, we investigated the role of STAT5a on migration in our model system." (PMID 19630967, 2009). "Furthermore, nuclear localization of STAT5A was negatively correlated with BCL6 expression in breast cancer tissue samples, where BCL6 expression is associated with increased proliferation and cell cycle progression and reduced differentiation." (PMID 40507264, 2025). "Subgroup analysis of adjusted HRs by cancer types showed that STAT5a expression was significantly associated with favorable overall survival in breast cancer (lnHR = −0.6091 [−1.0810, −0.1372], P-value = 0.0114) aligning with the results from a subgroup analysis of the unadjusted HRs." (PMID 37369132, 2023). "High STAT5a expression was significantly associated with favorable survival in bladder cancer (lnHR = −0.8689 [−1.4087, −0.3292], P-value = 0.0016), breast cancer (lnHR = −0.7805 [−1.1394, −0.4215], P-value < 0.0001) and lung cancer (lnHR = −0.3255 [−0.6427, −0.0083], P-value = 0.0443)." (PMID 37369132, 2023). "In summary, our systematic review study shows that high STAT5a expression is associated with favorable survival in breast cancer, suggesting that STAT5a could be a potential prognostic biomarker." (PMID 37369132, 2023). "As well, Stat5a expression in breast cancer clinical cases was found to associate with histologic differentiation (low grade) and favorable prognosis, whereas loss of Stat5a expression was associated with tumor progression, unfavorable prognosis and increased risk of failure to antiestrogen therapy." (PMID 36157462, 2022). "We hypothesized that expression of serine phospho-deficient STAT5a mutants would affect breast cancer transcriptomic programs and these alterations in gene expression patterns would lead to changes on a phenotypic scale." (PMID 34188118, 2021). "However, the role of Stat5a in breast cancer remains unsettled: elevated pY694-Stat5a in clinical samples associates with more differentiated tumors and better prognosis, yet Stat5a knock-out mice display delayed tumor onset." (PMID 33772010, 2021). "On the one hand, STAT5a promotes transformation of mammary epithelial cells and survival of breast cancer cells; on the other hand, STAT5a is associated with a relatively good prognosis for patient survival since it promotes mammary epithelial cell differentiation." (PMID 34336684, 2021). "PRL activates both Stat5a and Stat5b, which have 92% amino acid similarity, but are encoded by different genes and may mediate overlapping and distinct effects in breast cancer cells." (PMID 23758962, 2013). "Our novel observations suggest a selective loss of Stat5a protein during breast cancer progression, representing a newly defined mechanism to explain partially the observed frequent loss of Nuc-pYStat5a/b during breast cancer progression." (PMID 23036105, 2012). "Analysis of tumors from a second pair of independent cohorts of patients, who had received adjuvant antiestrogen monotherapy, identified loss of Nuc-Stat5a protein as an independent marker associated with greater than fourfold increased risk of death from breast cancer in this population." (PMID 23036105, 2012). "Interestingly, patients whose tumors were in the lowest quartile of Stat5a mRNA expression levels were associated with reduced time to breast cancer relapse, whereas the highest quartile of Stat5a mRNA expression levels associated with longer time to relapse." (PMID 23036105, 2012). "Loss of Stat5a protein may represent a new mechanism contributing to the reported frequent loss of Nuc-pYStat5a/b during breast cancer progression." (PMID 23036105, 2012).
breast cancer (continued). "Of note is the apparent inconsistency between the two breast cancer data sets with respect to the direct effect of STAT5A: Repression of STAT5A was associated with poor survival in the Dutch data set, whereas activation of the same protein correlated with poor survival in the Uppsala data set." (PMID 18358079, 2008). "Moreover, expression/activation of the PRL effector molecule Stat5a was found to associate positively with increased levels of histologic differentiation of breast cancer tissues and to distinguish breast cancer patients with favourable prognosis and response to endocrine therapy." (PMID 27480353, 2016). "In addition, the low expression levels of specific proteins have also been associated with cancer progression, such as the signal transducer and activator of transcription-5a, which showed reduced expression in primary breast cancer and is subsequently an independent marker of poor prognosis." (PMID 24932247, 2014). "We conclude that loss of Nuc-Stat5a in invasive breast cancer and metastases reflects, in part, loss of total cellular expression of Stat5a protein and is not simply a result of reduced tyrosine phosphorylation and nuclear translocation or due to increased nuclear exclusion of Stat5a." (PMID 23036105, 2012). "For example, STAT5A promotes doxorubicin resistance through transcriptional upregulation of ATP binding cassette subfamily B member 1 (ABCB1) in breast cancer." (PMID 40507264, 2025). "Specifically, OCT1 interacts with the transactivation domain of STAT5A to promote prolactin-induced cyclin D1 expression, which encourages cell cycle progression in breast cancer." (PMID 40507264, 2025). "It has been demonstrated that STAT5A is required for expression of NADPH oxidase 5 long form (NOX5-L) in HER2-positive SK-BR-3 breast cancer cells where NOX5-L inhibition reduced proliferation, migration, and invasion." (PMID 40507264, 2025). "This increases Stat5a-mediated transcription and elevates the protein expression of breast cancer proliferative genes, such as CISH, CEBPb (CCAAT/enhancer binding protein β), and cyclin D1, which promote the proliferation of breast cancer." (PMID 40092489, 2025). "For instance, IKZF3 and STAT5A overlap in immune-related pathways, while FOXP4 exhibits some distinct enrichment patterns associated with breast cancer, suggesting potential cooperative and specialized regulatory mechanisms." (PMID 40923764, 2025). "In contrast, STAT5A demonstrated divergent effects, conferring favorable survival in breast cancer but poorer outcomes in hematologic cancers." (PMID 41301421, 2025). "In the current study, STAT5A was first shown to be activated by Notch3 signaling in breast cancer, resulting in suppression of EMT and metastasis of breast cancer cells." (PMID 38124049, 2023). "The current study shows a role for STAT5A in suppression of invasion, as demonstrated by overexpression or knockdown of STAT5A in different breast cancer cell lines." (PMID 38124049, 2023). "In luminal breast cancer cell lines, an ERα-STAT5A complex was found, and its functional consequence depended on the precise milieu of the intracellular environment." (PMID 38124049, 2023). "Meanwhile, STAT5A has also been found to be an inducer of chemoresistance and facilitate the resistance of breast cancer to doxorubicin through regulating ABCB1." (PMID 38124049, 2023). "Conversely, knockdown of Notch3 by siRNA caused significant downregulation of STAT5A and lowered levels of p-STAT5 in breast cancer cell lines." (PMID 38124049, 2023). "It is found that prolactin-directed mammary epithelial cell differentiation program related to STAT5A offer a good prognosis in human breast cancer." (PMID 38124049, 2023). "Other than our study, it has also been reported that miR-100 promotes tumor metastasis in mouse breast cancer via the STAT5a/IL-1RA signaling pathway." (PMID 37461111, 2023).